FOXM1 (forkhead box M1)
Diseases named in the same sentence as FOXM1 in open-access papers (continued):
Sharing a sentence is not in itself a finding about the gene and the disease.
melanoma (continued). "Whereas the BRAFV600E-induced nevus showed only background staining for Pin1 and FoxM1, both were strongly elevated in a BRAFV600E-derived melanoma." (PMID 26279295, 2016). "We found that MEK1 siRNA downregulated the expression of FOXM1, together with p-MEK, in three melanoma cells (MeWo cells, MM-LH cells and VM115 cells)." (PMID 26640950, 2015). "We conducted an MEK siRNA analysis in four melanoma cell lines, and found that MEK1 siRNA downregulated the expression of FOXM1, together with p-MEK, in two melanoma cells." (PMID 26640950, 2015). "We found that LY294002 and the AKT inhibitor reduced the expression of FOXM1, thus suggesting that FOXM1 is regulated by the PI3K/AKT pathway in melanoma cells." (PMID 26640950, 2015). "FOXM1 expression was not significantly different between primary melanoma tissues and metastatic melanoma tissues (P > 0.05)." (PMID 35906389, 2022). "Hao and his colleagues found that EP300 could induce an increase in ALKBH5 expression to reduce the m6A level of FOXM1 mRNA by upregulating H3K27ac, resulting in enhanced FOXM1 mRNA levels and EMT cascade activation in melanoma." (PMID 36276071, 2022). "Receiver operating characteristic (ROC) curves showed an area under the curve (AUC) >90.0% for KPNA2, DTL, BACE2, DTYMK, E2F3 and SLC25A13, >80.0% for CCNA2, FOXM1, KIF4A, SLC45A2, COPS8, SLC45A13 and 70.0% for CDC25A and LINC00520; all significantly discriminating melanoma from benign nevi." (PMID 36320118, 2022). "The outcomes of immunohistochemistry experiments demonstrated that PDGFRB and FOXM1 were overexpressed in melanoma samples in comparison to normal tissues." (PMID 36467505, 2022). "In conclusion, by combining the WGCNA analysis method with differentially expressed gene analysis, our study identified the genes FOXM1, KIF20A, TPX2, CDC20, and EXO1 highly correlated with survival melanoma patients and have the potential to serve as a prognostic biomarker in melanoma." (PMID 33912448, 2021). "FOXM1, KIF20A, TPX2, CDC20, and EXO1 could be used as biomarkers for melanoma diagnosis, treatment, and prognosis prediction." (PMID 33912448, 2021). "Nonetheless, only a very small number of circRNAs are identified in melanoma yet and the effects of circ-FOXM1 in melanoma are still not very clear." (PMID 32183822, 2020). "Our data provided a novel regulatory network circ-FOXM1/miR-143-3p/FLOT2 axis in melanoma progression and might have a crucial implication for melanoma treatment." (PMID 32183822, 2020). "FOXM1 is involved in the transcriptional control of the epigenetic regulator EZH2, the latter gene being also a regulator of the EMT program and of the invasive activity and metastatic ability of melanoma cells." (PMID 30710146, 2019). "The Pin1-FOXM1 interaction was enhanced by BRAFV600E, the driver oncogene in the majority of melanomas, and in extrapolation of the correlation data, interference with\ Pin1 in BRAFV600E-driven metastatic melanoma cells impaired both FOXM1 activity and cell survival." (PMID 26279295, 2016). "Individual melanomas from independent data sets showed that FOXM1, CENPF and Cyclin B1, but not actin (control), significantly correlated with Pin1 expression." (PMID 26279295, 2016). "JQ1 was characterized by induction of inhibitory relationship linking regulators of inflammation (IFNG, IL17A, TGFB2), melanoma biological behavior (EGFR, WNT3A, TEADs, MRTFB), cell-cell interaction (CD44, CCN2), YAP pathway (LLGL2, NSUN6) and main transcriptional regulators (FOS, JUN, FOXM1)." (PMID 36397155, 2022). "In A375 melanoma cell lines, erastin, a ferroptosis activator, stimulates NEDD4 and FOXM1 expression, and it led to the ubiquitination and degradation of voltage-dependent anion channels, VDAC2/3, which further led to the suppression of erastin-induced ferroptosis in melanoma." (PMID 36293239, 2022).
melanoma (continued). "VDAC2 as a voltage-dependent anion channel was widely explored in multiple FRG prognostic models and bound directly with the ferroptosis activator erastin for increasing the sensitivity of cancer cells to ferroptosis via a FOXM1-Nedd4-VDAC2/3 negative feedback loop in melanoma." (PMID 36386203, 2022). "In A375 melanoma cell lines, erastin, a ferroptosis activator, stimulates the expression of NEDD4 and FOXM1 that leads to the ubiquitination and degradation of voltage-dependent anion channels, VDAC2/3, which further leads to the suppression of erastin-induced ferroptosis in melanoma." (PMID 36293239, 2022). "On this basis and according to available evidence on regulation of FOXM1 by Myc and on regulation and roles of FOXM1 and EZH2 in EMT, we tested the hypothesis that the EMT-like program of melanoma cells could be regulated by an axis connecting NFATc2 to EZH2, through c-Myc and FOXM1." (PMID 30710146, 2019). "Moreover, MAPKi-resistant melanoma cells consistently underwent a prominent increase of endogenous NOTCH1 levels and a cell-type dependent increase of the other two miR-204-5p targets RAD51 and FOXM1." (PMID 30254376, 2019). "In contrast to CDKN2A, which is known to be lost in many melanomas, we did not observe significant changes in FOXM1 gene copy number, suggesting the FOXM1 increase may be due to elevated transcription." (PMID 26279295, 2016). "However, the downregulation of FOXM1 by siRNA did not affect the expression levels of p-AKT in the melanoma cells." (PMID 26640950, 2015).
non-small cell lung carcinoma (46 papers, 2009 to 2024). A group of at least three distinct histological types of lung cancer, including non-small cell squamous cell carcinoma, adenocarcinoma, and large cell carcinoma. "Futhermore, enhanced expression of FoxM1 is associated with advanced stage, lymph node matastasis and acts as an independent prognostic factor in non-small cell lung cancer (NSCLC)." (PMID 25935853, 2015). "The Forkhead Box m1 (Foxm1) protein is induced in a majority of human non-small cell lung cancers and its expression is associated with poor prognosis." (PMID 19672312, 2009). "Furthermore, STMN1 overexpression is associated with upregulation of FOXM1 in patients with advanced non-small cell lung cancer, and STMN1/FOXM1 upregulation leads to poor prognosis." (PMID 36127700, 2022). "YAP regulates epithelial-to-mesenchymal transition (EMT)-induced resistance to EGFR TKI in non-small cell lung cancer (NSCLC) via FOXM1/SAC pathway." (PMID 38164167, 2024). "Research has shown that several downstream targets of FOXM1, including survivin, cyclin B1, S-Phase Kinase-Associated Protein 2, and CDC25B, were significantly upregulated in non-small-cell lung cancer cells treated with gefitinib." (PMID 37242455, 2023). "Another study showed that knockdown of circZNF609 inhibited cell malignant biological behavior but facilitated apoptosis and repressed xenograft tumor growth in development of non-small cell lung cancer via regulating miR-623 and FOXM1." (PMID 35135416, 2022). "Increased expression of FOXM1 has also been shown to significantly correlate with EMT marker proteins in tissue specimens from non-small cell lung cancer (NSCLC) patients." (PMID 34708244, 2022). "The AKT/FOXM1/STMN1 pathway was indicated to drive resistance to tyrosine kinase inhibitors in advanced non-small cell lung cancer including LSCC." (PMID 32993587, 2020). "Herein, we aimed to investigate biological function, molecular mechanism, and clinical significance of a circular RNA FOXM1 (circFOXM1) in non-small cell lung cancer (NSCLC)." (PMID 32228656, 2020). "Another study demonstrated that FOXM1 overexpression in non-small cell lung cancer cells was remarkably correlated with Gli1 expression, indicating SHH signaling activation." (PMID 24325450, 2013). "To further confirm the role of FoxM1 in the metastasis of non-small cell lung cancer, we developed a mouse model by tail vein injection of PC-9 FoxM1 overexpressing (PC-9-FoxM1) and control (PC-9-Vector) cells." (PMID 23536876, 2013). "FOXM1 is involved in TGF-β1–induced EMT, and TGF-β–based treatment has led to a dramatic increase in FOXM1 expression in non-small cell lung cancer cells." (PMID 24325450, 2013). "Increased Foxm1 levels were found in numerous types of human tumors, including non small cell lung cancer." (PMID 19672312, 2009). "For example, circHIPK3 can promote angiotensin II-induced cardiac fibrosis by sponging miR-29b-3p,35 and circ-FOXM1 facilitates cell progression by sponging miR-1304-5p in non-small-cell lung cancer, suggesting that the miRNA sponge effect of circRNAs is a vital mechanism." (PMID 32305019, 2020). "Since FOXM1 overexpression induces neoplastic transformation of breast epithelia, prostate epithelia, non-small cell lung cancer-derived cells, and oral cavity and esophageal epithelia, we silenced FOXM1 expression by introducing FOXM1-targeting short-hairpin RNAs (shRNA) into SCC-25 cells." (PMID 30978209, 2019). "In addition, miR-134 inhibits epithelial to mesenchymal transition by targeting FOXM1 (forkhead box protein M1) in non-small cell lung cancer cells." (PMID 26919096, 2016). "However, whether FoxM1 has any indication for prognosis in non-small cell lung cancer patients remains unclear." (PMID 23536876, 2013).
non-small cell lung carcinoma (continued). "For example, in a non-small-cell lung cancer (NSCLC) model, isolated CSCs exhibited elevated FOXM1, the knockdown of which resulted in reduced expression of stem cell markers (CD133 and CD44), stem cell regulators (Bmi1, Sox2, and Oct4), and self-renewal." (PMID 37174744, 2023). "Moreover, in non-small cell lung cancer cells, through Western blotting, researchers found that when CASC8 was knockdown, the level of FOXM1 protein decreased." (PMID 34199840, 2021). "Previous studies demonstrated ERK signaling could induce Forkhead Box M1 (FoxM1) to promote trophoblast cell invasion and mediate TGF-β-induced EMT in non-small cell lung cancer." (PMID 32471201, 2020). "Moreover, circ-FOXM1 promotes cell progression by sponging miR-1304-5p that targets PPDPF and MACC1 in non-small cell lung cancer; upregulated circ-FOXM1 facilitates cell proliferation and invasion via absorbing miR-1231 and miR-1304 in papillary thyroid cancer." (PMID 35799265, 2022). "Another finding revealed that FOXM1 upregulation by MnSOD overexpression induced the expression of the cancer stem cell (CSC)-related proteins Oct4, Nanog, and Sox2 in addition to Wnt/β-catenin to maintain self-renewal properties in non-small cell lung cancer stem-like cells (LCSLCs)." (PMID 30992007, 2019).
triple-negative breast carcinoma (46 papers, 2014 to 2025). An invasive breast carcinoma which is negative for expression of estrogen receptor (ER), progesterone receptor (PR), and human epidermal growth factor receptor 2 (HER2). "The transcription factor FOXM1 is upregulated and overexpressed in aggressive, therapy-resistant forms of hormone receptor-positive and triple negative breast cancers, and is associated with less good patient survival." (PMID 31815181, 2019). "Previously, our group showed the binding interaction between eEF2K and FOXM1 in triple negative breast cancer." (PMID 40725039, 2025). "FOXM1 is a pro-oncogenic transcription factor that is often upregulated in triple-negative breast cancer and aggressive solid cancers." (PMID 39594778, 2024). "We have also generated FOXM1-resistant estrogen receptor-positive and triple-negative breast cancer cells by culturing the cells continuously in increasingly high levels of NB73 for more than 6 months." (PMID 38980505, 2024). "We discovered an overdrive of a FOXM1-mediated transcriptional signaling cascade in AR-low relative to AR-high triple-negative breast cancers (TNBCs)." (PMID 39335162, 2024). "An effective CRBN-recruiting PROTAC, 17d, exerted a significant antitumor effect by functioning as a FOXM1 degrader in triple-negative breast cancer." (PMID 37288663, 2023). "By enhancing YAP1’s transcriptional activity, FOXM1 increased the capacity of triple-negative breast cancer cells to proliferate, form clones, and migrate." (PMID 37626655, 2023). "The observations reported here delineate mechanisms by which FOXM1 inhibitors can suppress ER-positive and triple negative breast cancer (TNBC) and the pathways that become altered in resistance." (PMID 34944900, 2021). "DEPDC1 was shown to be negatively regulated by miR-26b and promoted cell proliferation and tumor growth by upregulating FOXM1 expression in triple-negative breast cancer." (PMID 32149111, 2020). "It has been reported to stabilize FOXM1 by attenuating its ubiquitination in triple-negative breast cancer (TNBC), thus promoting proliferation of TNBC cells." (PMID 33391348, 2020). "Increasing evidence has demonstrated that FoxM1 accelerates tumor invasion and migration by regulating eukaryotic extension factor 2 kinase eEF2 in triple negative breast cancer." (PMID 32035486, 2020). "Our new findings expand upon previous studies in other types of cancer by showing FOXM1 to be a master regulator of triple negative breast cancer progression and metastasis." (PMID 32961773, 2020). "Consistently, higher FoxM1 mRNA levels were found in Basal-like or Triple-negative breast cancer (TNBC) patients." (PMID 29416660, 2018). "Upon hypoxia, active HIF-1α results in inactivation of PRC2 and release of EZH2, leading to functional switch to EZH2/Forkhead box M1 (FoxM1) complex-induced expression of MMPs and invasion in triple-negative breast cancer." (PMID 28561778, 2017). "In this study, we examined the role of Forkhead Box M1 (FOXM1) proto-oncogenic transcription factor in triple negative breast cancer (TNBC) cells and the regulation of eEF2K." (PMID 26918606, 2016). "The FOXM1 gene was also recently highlighted as significantly deregulated in serous ovarian tumors and metastatic triple-negative breast cancer." (PMID 24489661, 2014). "Moreover, the inhibition of USP7 has shown potential in triple-negative breast cancer by destabilizing FOXM1, thus suppressing tumor growth and underscoring its significance as a therapeutic target in cancer treatment." (PMID 40389405, 2025). "Interestingly however, samples low in ESR1 topic showed a high FOXM1 topic expression and predominantly consisted of triple negative breast cancer (TNBC) samples." (PMID 36318267, 2022). "The findings suggest that these FOXM1 suppressive compounds may have therapeutic potential in treating triple negative breast cancer, with the aim of reducing tumor progression and metastatic outgrowth." (PMID 32961773, 2020).
triple-negative breast carcinoma (continued). "Therefore, its role in cell cycle regulation and in transcriptional control of metastasis-related factors makes FOXM1 a unique therapeutic target in triple negative breast cancer." (PMID 32961773, 2020). "Since RAS can stimulates FOXM1 expression, our findings also might be used to explain how FOXM1 is up‐regulated by DEPDC1 in triple negative breast cancer cells, which was observed in another study." (PMID 33021072, 2020). "CBP/β-catenin/FOXM1 provides a molecular target for precision therapy in triple negative breast cancer and could form a rationale for potential clinical trials." (PMID 30572639, 2018). "In addition, they confirmed published findings on the impact of NB73 on triple negative breast cancer (TNBC) indicating that NB73 is superior to previously developed FOXM1 inhibitors such as FDI-6 and the peptide thiazole antibiotics, thiostrepton and siomycin A." (PMID 35794249, 2022). "Released EZH2 participates in the EZH2/Forkhead box M1 (FoxM1) complex and induces MMP expression and invasion in triple-negative breast cancer (TNBC)." (PMID 29556394, 2018). "Finally, in triple negative breast cancer cells, FZD5 enhanced DNA damage repair by upregulating FOXM1 in a β-catenin-dependent manner." (PMID 41286306, 2025). "In preclinical studies using two orthotopic triple-negative breast cancer (TNBC) xenograft models (MDA-MB-231 and MDA-MB-436), systemic intravenous administration of FOXM1-specific siRNA or miR-34a encapsulated in lipid nanoparticles significantly delayed tumor growth." (PMID 39594778, 2024). "Additionally, CDH6 correlated with stem-cell-related transcription factors, including FOXM1, SNAI1, SOX9, and MCM2, in triple-negative breast cancer." (PMID 35938030, 2022). "Additionally, besides triple negative breast cancer cells, FDI-6 also effectively suppressed the growth of FOXM1 expressing ER-positive MCF-7 cells in a dose dependent manner, and the IC50 was 3.227 ± 0.5.3 μM." (PMID 34206484, 2021).